NLRP3 (NLR family pyrin domain containing 3)
Diseases named in the same sentence as NLRP3 in open-access papers (continued):
Sharing a sentence is not in itself a finding about the gene and the disease.
allergic disease (continued). "This review delves into recent NLRP3 research, exploring its activation and regulation mechanisms, its role in allergic diseases, and its potential as a novel therapeutic target." (PMID 39131161, 2024). "As our understanding of the pharmacological effects of natural plants deepens, more studies are targeting the mechanisms of NLRP3 in allergic diseases." (PMID 39131161, 2024). "In summary, the activation of NLRP3 can not only act on the development of allergic diseases, e.g., by inducing Th2 cell differentiation, but also aggravate the disease and promote the deterioration of cell and organ function." (PMID 39131161, 2024). "Recent studies have highlighted the role of NLRP3-mediated pyroptosis in the development of allergic diseases." (PMID 39131161, 2024). "Although conducted in BALB/c mice, it has been shown that functional IL-1β signaling via NLRP3 is required in an ovalbumin-induced model of allergy." (PMID 38933263, 2024). "Accumulating evidence has demonstrated that activation of the NLRP3 inflammasome is involved in the development of allergic diseases, leading to its evaluation as a potential therapeutic target." (PMID 36033385, 2022). "Recently, it has been shown that NLRP-3 was an inflammatory compound widely existing in epithelial cells and played an important role in the occurrence and development of allergic diseases." (PMID 35782549, 2022). "The anti-allergy drug tranilast (TR) is also a direct NLRP3 inhibitor, which binds to the NACHT domain of NLRP3, inhibiting NLRP3 assembly by blocking its oligomerization." (PMID 35095918, 2021). "More recently, Tranilast (Rizaben), an anti-allergy drug derived from tryptophan, was identified as a specific inhibitor of NLRP3 inflammasome." (PMID 33499208, 2021). "To date, contradictory results were obtained regarding the role of NLRP3 in HDM-mediated allergy and the role of other NLRs in asthma is poorly understood." (PMID 33424827, 2020). "With further research, RRx-001 may emerge as a specific therapeutic small molecule for the treatment of NLRP3-mediated allergic diseases." (PMID 39131161, 2024). "Therefore, we aimed to develop a physiologic and adjuvant-free mouse model to study the involvement of NLRP3 in BP allergy." (PMID 38933263, 2024). "Potential mechanisms of several NLRP3 inflammasome inhibitors in allergic diseases." (PMID 39131161, 2024). "Furthermore, the activated NLRP3 inflammasome promotes the expression and regulation of various inflammatory factors, including IL-6, IL-17, and IL-33, participating in allergic disease development." (PMID 39131161, 2024). "OLT1177’s specific inhibition of NLRP3 inflammasomes offers a promising therapeutic approach to prevent the release of pro-inflammatory factors IL-1β and IL-18, potentially benefiting the treatment of allergic diseases." (PMID 39131161, 2024). "However, to really understand the role of NLRP3 in BP allergy as well as in other allergic disorders, a cell type-specific knockout or knock-in similar to what has already been established for the NAIP/NLRC4 inflammasome would be beneficial." (PMID 38933263, 2024). "Nowadays, novel specific NLRP3 inflammasome antagonists, which could reduce inflammation and support therapy in allergic diseases, have been sought." (PMID 36203607, 2022). "Furthermore, NLRP3 inhibition or deletion during early-life RSV infection led to reducing viral-exacerbated allergic response in a mouse model of RSV-induced allergy exacerbation." (PMID 33923693, 2021). "In addition, miRNA regulation of NLRP3 also plays a role in the progression of allergic diseases." (PMID 39131161, 2024). "However, further research is needed to fully understand NLRP3’s specific mechanisms in allergies." (PMID 39131161, 2024). "Therefore, NLRP3 inflammasome regulation may represent a novel therapeutic approach for the treatment of allergic diseases, including AD." (PMID 33520088, 2021).
allergic disease (continued). "Besides NLRP3 inhibitors, a number of novel anti-inflammatory and anti-allergy drugs might contribute to the treatment of AD via the NLRP3 pathway." (PMID 32792920, 2020). "To investigate the role of NLRP3 regarding airway epithelial barrier integrity in the context of allergic disease, we compared C57BL/6 (WT) and NLRP3 knock-out (NLRP3-/-) mice in a well-established experimental model of allergic airway disease." (PMID 41394833, 2025). "It operates by inhibiting the activities of NLRP3, caspase-1, and ASC, thereby reducing the secretion of IL-1β and IL-18 in various allergic diseases." (PMID 39131161, 2024). "NLRP3, a pivotal member of the NLR (nucleotide-binding oligomerization domain-like receptor) family, is increasingly recognized as a promising therapeutic target for a spectrum of conditions, including allergies." (PMID 39131161, 2024). "Contradictory data have been generated by studies showing that NLRP3 activation is not essential for allergic disease development in OVA and HDM induced AAI." (PMID 31590215, 2019). "Because NLRP3 is well described as an inflammasome-forming NLR but has also been described to act as a transcription factor, we next asked whether the induction of BP allergy in our sensitization model depends on NLRP3 as an inflammasome driver." (PMID 38933263, 2024). "Thus, there is no consensus view on the specific role of NLRP3 in the induction of different allergies." (PMID 38933263, 2024). "Tranilast has been used to inactivate the NLR family pyrin domain containing 3 (NLRP3) inflammasome, yet is also used as an anti-allergy medication as a “mast cell stabilizer” suggesting that its effect in the brain may also modulate mast cell functions via the inflammasome." (PMID 33499208, 2021). "Interestingly, unlike Th1 cytokines, allergy-related Th2 cytokines can downregulate the mRNA expression of NLRP3 and ASC in primary keratinocytes (HPK)." (PMID 33546184, 2021). "Given the role of NLRP3 in promoting allergic pathology, for example, it is not surprising that the phenotypic spectrum of CAPS comprises eosinophilia and clinical allergy in addition to systemic autoinflammation." (PMID 35281022, 2022).
atopic dermatitis (25 papers, 2018 to 2025). "There is a strong association between NLRP3 variant rs10733113 and an increase in the levels of serum IgE-specific antibodies in male individuals of Swedish families with atopic dermatitis." (PMID 33534121, 2021). "A significant correlation between the NLRP3 rs35829419 polymorphism and increased susceptibility to atopic dermatitis has been identified." (PMID 33534121, 2021). "Single-nucleotide polymorphisms (SNPs) of the Nlrp3 gene are associated with atopic dermatitis." (PMID 33534121, 2021). "NLRP3 inflammasome plays a positive role in the development of atopic dermatitis by house dust mite allergens, while impaired NLRP3 inflammasome activity under Th2-skewed conditions makes atopic dermatitis patients susceptible to S. aureus-mediated skin infection." (PMID 33534121, 2021). "HCIE exerts anti-inflammatory and anti-atopic dermatitis effects in human keratinocytes by modulating the MAPK/NF-κB/NLRP3 inflammasome, JAK1/STAT6 pathway, and skin moisturizing factors." (PMID 40777996, 2025). "The role of IL-18 in S. aureus infection is not yet fully understood, but it was shown in an atopic dermatitis (AD) mouse model that S. aureus increases the epidermal IL-18 production that was dependent on the activation of the NLRP3 inflammasome." (PMID 38571946, 2024). "The NLRP3 inflammasome facilitations the maturation of interleukin (IL)-1β, a proinflammatory cytokine that is critically involved in the pathogenesis of atopic dermatitis (AD)." (PMID 37175425, 2023). "The expression of NLRP3 and caspase-1 was lower in atopic dermatitis skin lesions compared to those in healthy skin." (PMID 33534121, 2021). "For instance, Niebuhr and co‐workers demonstrated that Staphylococcus aureus colonization and infection leads to NLRP3 inflammasome impairment, which contributes to chronic skin inflammation in atopic dermatitis." (PMID 33634989, 2021). "Allergens and atopic dermatitis triggers, such as S. aureus-derived compounds can also activate NLRP3 in monocytic cells, in human keratinocytes, and in mouse keratinocytes." (PMID 33925158, 2021). "Expression of NLRP3 and caspase-1 was significantly impaired in lesional skin of atopic dermatitis patients compared to healthy controls." (PMID 33925158, 2021). "Therefore, our results suggest that M. concanensis exerts anti-atopic dermatitis effects by inhibiting the NLRP3 inflammasome-mediated IL-1β." (PMID 36297328, 2022). "Dermatophagoides pteronyssinus, a house dust mite allergen, is an important etiology for the development of atopic dermatitis and induces assembly of the NLRP3 inflammasome complex resulting in caspase-1 activation and IL-1β and IL-18 release from keratinocytes." (PMID 33534121, 2021). "House dust mite allergens activate the NLRP3 inflammasome in the development of atopic dermatitis." (PMID 32528469, 2020). "The study data indicated that NGR1 might relieve atopic dermatitis via inhibiting inflammation through suppressing the NF-κB signaling pathway and NLRP3 inflammasome activation." (PMID 31737789, 2019). "Although genetic predispositions of NLRP3 have not been discovered for atopic dermatitis, experimental data suggests that activation of the NLRP3 inflammasome might play a role in the disease." (PMID 33925158, 2021). "Therefore, the NLRP3 inflammasome is apparently involved in the pathology of atopic dermatitis depending on the context of whether its activation has detrimental or beneficial effects on the manifestations of the disease." (PMID 33534121, 2021). "In summary, the present study demonstrated that NGR1 treatment inhibited the production of pro-inflammatory cytokines and NO in LPS treated AW264.7 cells, which might be mediated by inhibiting the activation of NF-κB/NLRP3 inflammation signaling pathway and might therefore relieve atopic dermatitis." (PMID 31737789, 2019).
atopic dermatitis (continued). "In atopic dermatitis models, quercetin shows potential as a targeted therapy, while coptisine alleviates inflammation by suppressing the TXNIP/NLRP3 inflammasome." (PMID 40612058, 2025).
cervical carcinoma (25 papers, 2017 to 2025). A carcinoma arising from either the exocervical squamous epithelium or the endocervical glandular epithelium. "Mutations in the NLRP3gene have previously been linked to certain forms of cancer, but there have not been any specific studies examining the association between NLRP3 polymorphisms and cervical cancer (CC)." (PMID 37885032, 2023). "NLRP3 rs10754558 is associated with increased cervical cancer risk." (PMID 39769450, 2024). "For example, elevated ROS levels in cervical cancer induce NLRP3 inflammasome assembly and caspase-1 activation, ultimately leading to pyroptosis." (PMID 41226386, 2025). "miRNA-214 promotes pyroptosis in cervical cancer cells by enhancing NLRP3 expression, thus inhibiting cancer progression." (PMID 40718836, 2025). "Further, a natural antioxidant, polydatin, has been shown to prevent ovarian and cervical cancers by inhibiting NLRP3 inflammasome activation." (PMID 39769450, 2024). "This study found that CD200Fc inhibits LPS-induced NLRP3 inflammasome activation and release of IL-1β in SiHa and Caski human cervical cancer cells." (PMID 39769450, 2024). "In cervical cancer, ROS can activate NLRP3 inflammasomes, leading to apoptosis of cervical cancer cells." (PMID 39011036, 2024). "This study was therefore designed to investigate the effect of NLRP3 gene polymorphisms on HPV infection and cervical cancer in southern Chinese population." (PMID 37885032, 2023). "Upregulation of miR-214 triggered caspase-1-mediated pyroptosis and suppressed the proliferation of cervical cancer cells by upregulating NLRP3." (PMID 36387211, 2022). "The ROS model is mainly used to activate the NLRP3 inflammasome to induce pyroptosis of cervical cancer cells." (PMID 36497244, 2022). "Reactive oxygen species activate the NLRP3 inflammasome to induce pyroptosis in cervical cancer cells, and then participate in tumor progression." (PMID 36233009, 2022). "Upregulation of microRNA-214 (MiR-214) in cervical cancer patients and cervical cancer cell lines promotes pyroptosis of cervical cancer cells by enhancing NLRP3 expression." (PMID 36497244, 2022). "In cervical cancer, the NLRP3 inflammasome is mainly activated by reactive oxygen species to induce pyroptosis." (PMID 36199146, 2022). "The upregulation of Mir-214 in cervical cancer patients and cervical cancer cell lines can promote pyroptosis of cervical cancer cells by enhancing NLRP3 expression." (PMID 35883480, 2022). "miR-214 and NLRP3 were lowly expressed in cervical cancer patients and cervical cancer cells compared to their normal counterparts." (PMID 36387211, 2022). "Studies have shown that the NLRP3 inflammasome is involved in the innate immune response to cervical cancer, and its expression is widely present in tumor cells." (PMID 36199146, 2022). "Nevertheless, in cervical cancer, miR-214 targets NLRP3 and thereafter induces pyroptosis in cervical cancer." (PMID 36059539, 2022). "This NLRP3 regulatory mechanism is similar to what has been described for insulin-like growth factor-I shown to induce NLRP3 activation via ROS accumulation in HeLa cervical carcinoma cells." (PMID 34638239, 2021). "In a study using LPS-stimulated human CC cells, human SiHa and Caski cells (HPV-16-infected cervical cancer cell lines), the mRNA and protein levels of inflammasome components, such as NLRP3, pro-IL-1β, IL-1β, and caspase-1, was significantly increased." (PMID 33584639, 2020). "NLRP3 inflammasome is highly related to multiple gynecological disorders and obstetrical complications, such as cervical cancer (CC), preterm labor, FGR, RPL, PE, intrauterine fetal death, and NHIE." (PMID 33584639, 2020). "It has become clear that the NLRP3 inflammasome is involved in a broad spectrum of gynecological diseases such as cervical cancer, preterm labor, postpartum inflammation, and mycoplasma and chlamydia infection." (PMID 32595419, 2020).
cervical carcinoma (continued). "The activation of NF-κB leads to activation of the NLRP3 inflammasome and cytokine secretion, which plays an important role in cervical cancer progression." (PMID 28402258, 2017). "CD200Fc inhibits NLRP3 activation in cervical cancer cells by reducing IL-1β production." (PMID 39769450, 2024). "miRNA-214 increases NLRP3, promotes pyroptosis and reduces cervical cancer cell proliferation." (PMID 39769450, 2024). "NLRP3 polymorphisms are linked to HPV infection risk and cervical cancer progression." (PMID 39769450, 2024). "In addition, NLRP3 has been implicated in promoting epithelial–mesenchymal transition (EMT) in ovarian and cervical cancer cells, a critical process for cancer metastasis and progression." (PMID 39769450, 2024). "NLRP3 is also involved in innate immune response during cervical cancer." (PMID 36233009, 2022). "The possible molecular mechanisms of NLRP3 inflammasome has been proposed in cervical cancer." (PMID 33584639, 2020). "Epistasis analysis revealed that NLRP3 variants together with polymorphisms in inflammasome-related genes modulate both the frequency of inflammasome activation and the process of IL-1β and IL-18 maturation that influence HPV infection outcome and cervical cancer progression." (PMID 33613533, 2020). "Others have reported that CD200 (a membrane glycoprotein belongs to immune globulin super family) can suppress NLRP3 and TLR4-NF-κB pathways in LPS-induced human cervical cancer cell lines." (PMID 30447690, 2018). "Down-regulation of SYVN1 leads to the accumulation of NLR family pyrin domain containing 3 (NLRP3) protein by suppressing its ubiquitination/proteasomal degradation, leading to the activation of NLRP3/IL-1β/Smad2/3 axis, and eventually, epithelial–mesenchymal transition in cervical cancer." (PMID 40584294, 2025).
liver cancer (25 papers, 2015 to 2026). An epithelial or non-epithelial malignant neoplasm that arises from the liver. "Once HCC formed, the NLRP3 inflammasome components were significantly under-expressed in the transformed liver cancer cells demonstrating that these malignant cells originated from NLRP3 inflammasome-deficient precursor cells." (PMID 36763290, 2023). "For HCC, the NLRP3 inflammasome components are lost or significantly downregulated in liver cancer tissues, and the greater the deficiency of inflammasomes, the more advanced the cancer progression is." (PMID 31429707, 2019). "NLRP3 inflammasome initiation is linked with the onset of liver cancer, particularly HCC." (PMID 38143439, 2023). "In liver cancer, the downregulation of ERβ leads to the inhibition of the NLRP3 inflammasome, thereby promoting the progression of liver cancer." (PMID 38523155, 2024). "NLRP3 expression is down-regulated in liver cancer and closely related to prognosis, as evidenced by work, suggesting that NLRP3 exert effects on liver cancer." (PMID 37705746, 2023). "Similar to the NLRP3 inflammasome in liver cancer, the AIM2 inflammasome also possesses similar anti-tumor effects." (PMID 37705746, 2023). "Silencing of SNHG7 lowered SIRT1 expression, but elevated the expression of NLRP3, caspase-1 and IL-β, eventually contributing to pyroptosis in liver cancer cells." (PMID 36387211, 2022). "The SNHG7/miR-34a/SIRT1 axis played an important role in liver cancer progression via modulation of NLRP3-dependent pyroptosis." (PMID 36387211, 2022). "In liver cancer, NLRP3-related pyroptosis pathway suppressed by SNHG7 through regulation of miR-34a/SIRT1 ceRNA axis." (PMID 34488540, 2021). "A liver cancer study revealed reduced expression of NLRP3 inflammasome components in different stage of hepatocarcinogenesis (HCC)." (PMID 26378020, 2015). "Inhibits NLRP3-dependent pyroptosis via miR-34a/SIRT1 axis in liver cancer." (PMID 39267831, 2024). "Additionally, the expression of the inflammasome component of NLRP3 in patients with advanced liver cancer was even lower." (PMID 38182564, 2024). "Overexpression of SNHG7 impeded NLRP3-dependent pyroptosis in liver cancer cells." (PMID 36387211, 2022). "Wei and others showed that during the development of HCC, the NLRP3 components are dysregulated depending on the disease stage, while in the inflammatory hepatic setting it copes with IL-1β and NLRP3 upregulation, and malignantly transformed liver cancer is downregulated." (PMID 36289606, 2022). "Therefore, whether EVA1A can regulate autophagy/NLRP3 to improve liver cancer is a topic worthy of study in the future." (PMID 35743108, 2022). "In liver cancer, lncRNA small nucleolar RNA host gene 7 (SNHG7) suppresses NLRP3-triggered pyroptosis through the miR-34a/SIRT1 pathway." (PMID 39267831, 2024). "Thus, these genes may play a similar role in bladder cancer as NLRP3 in liver cancer." (PMID 35846123, 2022). "The NLRP3 inflammasome expression levels also showed a negative correlation with pathological grade and clinical stage in patients with liver cancer." (PMID 38182564, 2024). "In liver cancer, SNHG7 suppressed the NLRP3-related pyroptosis pathway." (PMID 36685973, 2022). "Interference with SNHG7 down-regulated the expression of SIRT1, but up-regulated the levels of NLRP3, caspase-1, and interleukin-1beta, which induced pyroptosis, suggesting NLRP3-dependent pyroptosis was induced through SNHG7/miR-34a/SIRT1 signaling pathway during liver cancer." (PMID 34381023, 2021).